GNAS (GNAS complex locus)
Diseases named in the same sentence as GNAS in open-access papers (continued):
Sharing a sentence is not in itself a finding about the gene and the disease.
pyloric gland adenoma (6 papers, 2013 to 2026). A rare neoplastic polyp that arises from the stomach. "The protein kinase A, activated by GNAS mutations, might play a role in Wnt pathway activation in pyloric gland adenomas by stabilizing β-catenin." (PMID 33922305, 2021). "Recently, it was suggested that GNAS-mutations are common in pyloric gland adenomas of the stomach and duodenal mucosa and may thus also specify a particular phenotype of GC." (PMID 28683819, 2017). "Similarly, frequent concurrent presence of KRAS and GNAS mutations was also detected in colorectal villous adenomas and pyloric gland adenomas." (PMID 24312577, 2013). "Interestingly, in duodenal adenocarcinoma, GNAS mutation was associated with gastric phenotype, suggesting that pyloric gland adenomas might represent the precursor lesions of duodenal adenocarcinomas with gastric differentiation." (PMID 33922305, 2021). "GNAS and KRAS mutations are frequently observed in pyloric gland adenomas and gastric‐type adenocarcinomas and are considered to represent characteristic molecular alterations in G‐type NADETs." (PMID 40964650, 2026). "Additionally, GNAS and KRAS mutations have been frequently observed in pyloric gland adenoma, IPMNs, and pancreatic intraepithelial neoplasia, respectively." (PMID 37371022, 2023). "Indeed, molecular changes reported in pyloric gland adenomas, such as GNAS and KRAS gene alterations, were also found in areas of gastric heterotopia of the duodenum." (PMID 33922305, 2021).
adrenocortical tumors (5 papers, 2021 to 2024). "Among these can be mentioned GNAS Complex locus (GNAS) which is known to be mutated in a subset of adrenocortical tumors." (PMID 38864697, 2024). "According to the authors’ knowledge, there was only one report where GNAS mutations were identified in canine adrenocortical tumors." (PMID 36151521, 2022). "Although cortisol-producing adenomas (CPAs), a leading cause of adrenocortical tumours, are mostly caused by somatic mutations in genes such as GNAS or PRKACA, how CPAs arise from a precursor lesion with genetic mutations in adrenocortical tissues remains to be elucidated." (PMID 38570222, 2024). "Furthermore, somatic inactivating variants in GNAS and PRKAR1A have been found in sporadic adrenocortical tumors." (PMID 36105398, 2022). "Furthermore, in a cohort of patients with adrenocortical tumors without variants in PRKAR1A, GNAS, or PDE11A, 7 patients harbored variants in PDE8B." (PMID 36105398, 2022).
appendiceal adenocarcinoma (5 papers, 2017 to 2026). "Beyond these alterations, GNAS mutations appear to be a distinct molecular feature of appendiceal adenocarcinoma." (PMID 41154355, 2025).
Cognitive impairment (5 papers, 2017 to 2024). Abnormal cognition is characterized by deficits in thinking, reasoning, or remembering. "However, cognitive impairment is seen rarely in patients with paternally inherited GNAS mutations (PPHP, POH) ranging from 0% to 10% of cases." (PMID 29280743, 2017). "A significant proportion of patients (40-70%) with a maternal coding mutation of GNAS, (formerly PHP-Ia) has been shown to have cognitive impairment." (PMID 29280743, 2017).
COVID-19 (5 papers, 2021 to 2024). A disease caused by infection with severe acute respiratory syndrome coronavirus 2. "We observed that functions of GNAS could also be associated with programmed cell death in COVID-19, possibly due to overlapping growth factor signals that may affect RAS signaling." (PMID 39502570, 2024). "Plasma proteomic analyses showed that this pattern was variably observed among COVID-19 patients, potentially involving calcium dysregulation and GNAS-regulated activities, ultimately impacting the regulation of microvascular permeability." (PMID 39502570, 2024). "The observed alterations in calcium channel function and GNAS-controlled activities could lead to disruptions in the regulation of vascular permeability, which may, in turn, induce endocrine resistance in the context of COVID-19." (PMID 39502570, 2024). "Eight genes associated with platelet activation and pro-thrombosis were upregulated in COVID-19 patients: MPIG6B, HBB, HPSE, CD40LG, STXBP3, CLEC1B, TFPI and GNAS." (PMID 35477940, 2022). "Regardless of the tissue type, we saw consistent increases in genes such as B2M, CD81, GNAS, HLA.B, HSPA1A, HSPB1, and SERPING1 in COVID-19 lungs." (PMID 35233546, 2022). "Interestingly we found six lncRNAs (TALAM1, DLEU2, and UICLM CASC18, SNHG20, and GNAS) involved in the protein-coding DEG-lncRNA network; which might be served as potential biomarkers for COVID-19 patients." (PMID 34975833, 2021).
cystic neoplasm (5 papers, 2021 to 2025). A benign or malignant neoplasm that contains a single or multiple cystic spaces. "Given that membrane localization of GNAS is typically associated with an inactive state, these observations indicate that the formation of cystic neoplasms in NRF2-deficient pancreata likely occurs through mechanisms independent of canonical GNAS activation." (PMID 40407127, 2025). "Genetically engineered mouse models have provided critical insights into the molecular pathways driving IPMN, demonstrating that combined GNAS and KRAS mutations induce cystic neoplasms that closely resemble human IPMN." (PMID 40407127, 2025). "However, the most common molecular alterations found in ductal adenocarcinoma (KRAS), cystic neoplasms (GNAS and RNF43), and NENs (MEN1, DAXX, and ATRX) are rarely found in ACC." (PMID 41120769, 2025). "With the aim of distinguishing MCNs from other PCNs, such as IPMN and SPN, some research have revealed that MCN is a kind of cystic neoplasm without the GNAS mutation and generally without the CTNNB1 mutation." (PMID 35299739, 2022).
dyslipidemia (5 papers, 2008 to 2025). "Seven genes (WDR27, GNAS, DOK7, EDN3, MCF2L, PRKG1, and CMYA5) were selected based on genomic location and relevance to metabolic syndrome." (PMID 31170227, 2019). "We investigated the correlation of DNA methylation with expression of seven genes (WDR27, GNAS, DOK7, EDN3, CMYA5, PRKG1, and MCF2L) selected on the basis of their known functions in metabolic syndrome, and their locations in functional genomic regions." (PMID 31170227, 2019). "These limited data indicate that under-nutrition at early life does not affect DNA methylation at GNAS DMR and the methylation level may not be associated with preeclampsia-induced risk of metabolic syndrome." (PMID 23844573, 2013).
hypothyroidism (5 papers, 2022 to 2025). Abnormally low levels of thyroid hormone. "We also prioritised a cryptic splice variant in GNAS (SpliceAI=0.67) in a participant with hypothyroidism." (PMID 37745552, 2023). "In that case, the hypothyroidism was attributed to both autoimmune thyroiditis and TSH resistance caused by a GNAS mutation." (PMID 41170251, 2025).
infertile (5 papers, 2018 to 2024). "Low methylation at GNAS has also been reported to be more prevalent in idiopathic infertile males, particularly in oligozoospermic males." (PMID 38012716, 2023). "In total, we identified the aberrant methylation of H19, GNAS, and DIRAS3 in 19.3%, 21.5%, and 22.2% of the 135 infertile males, respectively." (PMID 30373665, 2018). "In addition, we assessed four ICRs for different GNAS transcripts, as according to 3D cohort data, this imprinted locus is highly affected by ART/infertility in the placenta." (PMID 37170172, 2023).
invasive carcinoma (5 papers, 2015 to 2023). A carcinoma that is not confined to the epithelium, and has spread to the surrounding stroma. "Thus, Wu and coworkers reported the mutation of the oncogene GNAS occurring in about 66% of IPMNs: importantly, in the large majority of IPMNs progressing to PDAs with GNAS mutations, the mutation of this gene was observed also at the level of the invasive carcinoma." (PMID 29156578, 2017).
malaria (5 papers, 2012 to 2022). Malaria is a serious and sometimes fatal disease caused by a parasite that commonly infects a certain type of mosquito which feeds on humans. "A linkage between the GNAS c.393C>T polymorphism and susceptibility to malaria was observed in a study involving a South Indian population." (PMID 36297195, 2022). "The protective effect of rs8386 with anaemia observed in this study is in line with recent reports of an association between G-alpha-s gene (GNAS) polymorphisms with severe malaria, although the SNP was only significant in multi-locus associations." (PMID 24934404, 2014). "Likewise, although significant associations were seen between severe malaria and polymorphisms in seven additional genes (IL10, LPHN2 [ADGRL2], LOC727982, ARL14, RPS6KL1, CAND1, and GNAS), without further data their potential for translation remains elusive." (PMID 30033078, 2018).
pseudomyxoma peritonei (5 papers, 2022 to 2025). An appendix cancer that is characterized by progressive accumulation of mucus-secreting tumor cells within the abdomen and pelvis. "Examinations of pseudomyxoma from the appendix revealed that KRAS and GNAS pathogenic mutations are prevalent genetic characteristics of pseudomyxoma peritonei." (PMID 38672528, 2024). "Molecular analyses of pseudomyxoma from the appendix showed that KRAS and GNAS pathogenic variants are common genetic features of pseudomyxoma peritonei." (PMID 35255903, 2022). "Molecular analyses of appendiceal pseudomyxoma showed that KRAS and GNAS pathogenic variants are common genetic features of pseudomyxoma peritonei." (PMID 35255903, 2022). "In pseudomyxoma peritonei (PMP), KRAS and GNAS mutations are frequent." (PMID 37509688, 2023).
sarcoma (5 papers, 2021 to 2025). A usually aggressive malignant neoplasm of the soft tissue or bone. "Collectively, GNAS mutations were retained in most of the sarcomas (8/10), with more R201C (75%) than R201H (25%) mutations." (PMID 34989160, 2022). "More importantly, WES analysis was performed, which revealed significant SNA and CNA involvement on the basis of GNAS activating mutations in sarcomas, adding novel and valuable insight into genome alterations underlying FD malignancy." (PMID 34989160, 2022).
adrenocortical carcinoma (4 papers, 2018 to 2025). "Indeed, around 7% of adrenocortical carcinomas in TCGA have a mutation in the Gαs subfamily (GNAS and GNAL)." (PMID 40969301, 2025).
brain tumor (4 papers, 2010 to 2024). "Of note, ANXA1, ANXA2, GNAS, HSP90AA1, HSP90AB1 and PSMD2, were highly abundant in EVs captured from GBM neurosurgical aspirates and in Pre-OP GBM uEVs here, implicating a potential brain tumour diagnostic utility for TRiC subunits and their interacting partners." (PMID 38212481, 2024).
chondrosarcoma (4 papers, 2020 to 2025). A malignant cartilaginous matrix-producing mesenchymal neoplasm arising from the bone and soft tissue. "In another study, the same group used the ddPCR assay to analyse ctDNA in pre- and postoperative blood samples of 83 chondrosarcoma patients with known IDH1/2 or GNAS hotspot mutations." (PMID 39797974, 2025).
Insulin resistance (4 papers, 2014 to 2023). Increased resistance towards insulin, that is, diminished effectiveness of insulin in reducing blood glucose levels. "For example, GLP1R1 and GNAS proteins were related to insulin resistance." (PMID 36686441, 2022). "GLP1R, GNAS, and GCG were related to insulin resistance, which were verified by the previous studies." (PMID 36686441, 2022).
Mazabraud syndrome (4 papers, 2017 to 2026). Mazabraud syndrome is a rare primary bone dysplasia characterized by the association of fibrous dysplasia with intramuscular myxomas. "Mazabraud syndrome should be considered in patients with multiple or recurrent IMMs and GNAS mutations." (PMID 41827960, 2026). "Both characteristic lesions of Mazabraud's syndrome have been found to carry a mutation in the GNAS-1 gene." (PMID 39536670, 2024).
acrodysostosis (3 papers, 2023 to 2025). Acrodysostosis (ACRDYS) is a rare primary bone dysplasia characterized by severe brachydactyly, peripheral dysostosis with facial dysostosis, nasal hypoplasia, and developmental delay. "However, unlike PRMT7-related disorder, these are all autosomal dominant disorders caused by heterozygous variants in GNAS (PHP 1A and 1C), PRKAR1A and PDE4D (acrodysostosis), and/or 2q37 deletion resulting in loss of the HDAC4." (PMID 36399134, 2023).
Anxiety (3 papers, 2017 to 2019). Intense feelings of nervousness, tension, or panic often arise in response to interpersonal stresses. "In a recent study that investigated the epigenetic profiles of select youth, monozygotic twin pairs who were discordant for anxiety, the differential methylation of loci that were annotated to GNAS was associated with anxiety." (PMID 31639064, 2019). "Annotation of the anxiety-related DMRs to genes revealed 183 genes, many of which were known stress-related genes such as NAV1, IGF2, GNAS, and CRTC1." (PMID 29225348, 2017).
brachydactyly (3 papers, 2017 to 2024). A disease characterized by the presence of brachydactyly, including syndromic and non-syndromic forms. "We found a higher prevalence of brachydactyly, round face, intellectual disability and subcutaneous/heterotopic ossifications in patients with the c.565_568delGACT as compared to the other variants in the GNAS gene." (PMID 39456695, 2024). "Of the 22 GNAS mutations detected in GOOS participants, 5 had brachydactyly and 2 had evidence of TSH or PTH resistance with onset at 8 and 26 years." (PMID 39104441, 2024).
colorectal adenocarcinoma (3 papers, 2014 to 2024). The most common type of colorectal carcinoma. "Somatic activating mutations in GNAS have rarely been identified in the setting of colorectal adenocarcinoma." (PMID 39309469, 2024). "Pyrosequencing detected activating mutations of GNAS codon 201 in ten of the 428 (2.3%) colorectal adenocarcinomas." (PMID 24498230, 2014). "The prognostic and therapeutic significance of GNAS mutations in the setting of colorectal adenocarcinoma is currently unknown." (PMID 39309469, 2024).
fibrodysplasia ossificans progressiva (3 papers, 2020 to 2024). Fibrodysplasia ossificans progressiva (FOP) is a severely disabling heritable disorder of connective tissue characterized by congenital malformations of the great toes and progressive heterotopic ossification that forms qualitatively normal bone in characteristic extraskeletal sites. "Fibrodysplasia ossificans progressiva is caused by ACVR1 gene mutations, while progressive osseous heteroplasia is caused by GNAS gene mutations." (PMID 39620561, 2024).
male infertility (3 papers, 2018 to 2024). The inability of the male to effect fertilization of an ovum after a specified period of unprotected intercourse. "GNAS is involved in G protein-coupled receptor signaling, and differentially methylated regions in GNAS may be associated with idiopathic male infertility." (PMID 38012716, 2023). "Methylation anomalies of the H19, IGF2, GNAS, GNASAS, and MEST imprinted genes have not previously been associated with male infertility based on transcriptome data." (PMID 39017772, 2024).
metastatic tumor (3 papers, 2015 to 2025). "In case number 2, the primary tumour had an exon 8 GNAS mutation whereas the metastatic tumour was wild type." (PMID 37670299, 2023).
mucinous adenocarcinoma of the appendix (3 papers, 2020 to 2023). Mucinous adenocarcinoma of the appendix is a very rare, slow growing, well-differentiated epithelial neoplasm of the appendix characterized by abundant mucin production. "By histological subtype, young patients with mucinous adenocarcinomas of the appendix had 65% decreased odds of variations in GNAS compared with late-onset cases in adjusted models (OR, 0.35; 95% CI, 0.15-0.79; P = .01)." (PMID 33295976, 2020). "Stratification of patients by histological subtype revealed that young patients with mucinous adenocarcinomas of the appendix had 65% decreased odds of nonsilent variations in GNAS (OR, 0.35; 95% CI, 0.15-0.79; P = .01) compared with late-onset cases in adjusted models (eTable 3 in the Supplement)." (PMID 33295976, 2020).
osteofibrous dysplasia (3 papers, 2012 to 2025). A benign, usually self-limited fibro-osseous lesion of the bone that affects infants and children. "Also, cases of osteofibrous dysplasia have not shown any GNAS mutation." (PMID 23230423, 2012).
preeclampsia (3 papers, 2013 to 2015). Preeclampsia is a hypertensive disorder of pregnancy that is characterized by new-onset hypertension with proteinuria presenting after 20 weeks of gestation, and depending on mild or severe forms may initially present with severe headache, visual disturbances, and hyperreflexia. "At the individual gene level, IGF2 but not GNAS has been found to be significantly hypomethylated in cord blood cells associated with maternal preeclampsia." (PMID 25806090, 2015). "There were no any significant differences in the methylation levels at 7 sites of GNAS DMR among normal pregnancy, gestational hypertension and preeclampsia (P>0.05 for all)." (PMID 23844573, 2013). "They found that the average methylation level of IGF2 but not GNAS was significantly lower in the preeclampsia samples." (PMID 25806090, 2015). "Small-for-gestational age (SGA) and preeclampsia, conditions characterized by poor nutrient supply to fetus, induces hypomethylation at IGF2 and GNAS DMRs and altered methylation at DMRs of imprinted genes may subsequently contribute to the development of metabolic diseases in later life." (PMID 25269528, 2014). "However, the effect of GDM, a condition apposite to SGA and preeclampsia, on the methylation at DMRs of IGF2 and GNAS of fetus has not been described yet." (PMID 25269528, 2014).
psoriasis (3 papers, 2002 to 2024). An autoimmune condition characterized by red, well-delineated plaques with silvery scales that are usually on the extensor surfaces and scalp. "And the result displayed that three hub genes (GNAS, AUC = 0.709; IGF2, AUC = 0.644; and SNRPN, AUC = 0.926) had a credible diagnostic value for psoriasis." (PMID 37935955, 2023). "We speculate that GNAS may indirectly affect the development of psoriasis due to its role in immune response and cell proliferation." (PMID 38915827, 2024). "We identified GZMB, GNAS, GBP5, FOXP3, LSP1 and CD81 as characteristic genes of psoriasis-associated CD8+ T cells, among which, Granzyme B (GzmB), a serine protease, is produced by natural killer (NK) cells and CD8+ T cells, and is an vital mediator of skin injury, inflammation and repair." (PMID 38915827, 2024). "Similarly, decreased expression level of GNAS in CD8+ T cells also promotes the development of psoriasis." (PMID 38915827, 2024). "We first identified three hub genes, including SNRPN, IGF2, and GNAS, which could be potential therapeutic targets of psoriasis and T2D." (PMID 37935955, 2023).
serous cystadenoma (3 papers, 2016 to 2023). A serous neoplasm in which the cysts and papillae are lined by a single layer of cells without atypia, architectural complexity or invasion. "The KRAS (OR 7.4 and 71.2) and GNAS (OR 30.2 and 15.3) mutations were more frequently found in IPMNs than in mucinous cystic neoplasms and in serous cystadenomas, respectively." (PMID 27512631, 2016). "Four and five studies addressed KRAS and GNAS mutations between IPMN and serous cystadenoma (SCA) patients, respectively." (PMID 27512631, 2016).